IL6 (interleukin 6)
Diseases named in the same sentence as IL6 in open-access papers (continued):
Sharing a sentence is not in itself a finding about the gene and the disease.
depression (continued). "IL-6 induces pain, fatigue, and psychiatric disorders such as depression and stress, while IL-8 is associated with pain and sleep disorders." (PMID 37760809, 2023). "Growing evidence has also confirmed the association between chronic inflammation and depression, manifested with increased C-reactive protein levels and proinflammatory cytokines, such as IL-1 β, IL-6, and TNF-α." (PMID 38138916, 2023). "It has been suggested that has-miR-11399 regulates interleukin 6 (IL-6), associating it with vascular events, stress, and depression." (PMID 37566020, 2023). "Specifically, women with rheumatoid arthritis have elevated CRP and IL-6 levels, which contribute to the heightened risk of depression in female patients." (PMID 38062440, 2023). "Several studies have reported that inflammation in the brain and the associated over-release of pro-inflammatory cytokines TNF-α, IL-6, or IL-1β can lead to a loss of hippocampal neurogenesis, promoting depression-like behaviors." (PMID 37238920, 2023). "For example, levels of peripheral C-reactive protein (CRP)—an acute phase reactant that is synthesized by hepatocytes in response to pro-inflammatory cytokines (in particular interleukin-6 (IL-6))—are associated with overall depression severity." (PMID 36831896, 2023). "For example, the IL6-174G/C polymorphism in interaction with various stress factors increases the risk of depression, and the IL1B-511C/T was associated with more severe depression following chronic interpersonal stress exposure." (PMID 37510364, 2023). "Serum levels of C-reactive protein (CRP) and interleukin-6 (IL-6) have been associated with anxiety and depression in cross-sectional and Mendelian randomisation studies, but results regarding the effect size and direction have been mixed." (PMID 37217205, 2023). "This chronic inflammation, especially characterized by imbalances in IL-6 cytokine levels, has been found to be associated with anxiety, depression, and traumatic stress." (PMID 37867774, 2023). "It gives RA the possibility of causing depression and anxiety because of the hardship and deteriorating quality of life, and as an organic cause of elevated IL-6 levels." (PMID 37346903, 2023). "Genetically-predicted IL-6 was associated with major depression in a multivariable mendelian randomization study (OR = 1.08; 95% C.I., 1.03–1.12)." (PMID 37510364, 2023). "Nuclear factor I-A (NFIA) has been identified as the direct target for miR-212 which in turn regulates the level of the inflammatory factors TNF-α, IL-1β, and IL-6, which are generally associated with depression in human studies." (PMID 40655973, 2023). "IL-6 has also been linked to a number of psychiatric disorders such as anxiety, depression, and of relevance to the present study, suicidal ideation and behavior." (PMID 37779624, 2023). "Elevated level of cytokines particularly IL-6 was implicated in a wide array of manifestations including fatigue, anxiety, depression, olfactory dysfunction, orthostatic hypotension as well as pulmonary fibrosis." (PMID 36308638, 2023). "We discovered that LPS administration increased the serum levels of inflammatory cytokines such as TNF-α and IL-6, which have been linked to the etiology of depression." (PMID 36909194, 2023). "In longitudinal analyses, higher IL-6 predicted subsequent chronic course of depression and is more likely to be a risk factor for depression." (PMID 37304432, 2023). "Univariate logistic regression analysis showed that preoperative severe depression was associated with a higher preoperative serum IL-6 level (> 1.985 pg/mL) (p = 0.010)." (PMID 37324195, 2023). "Circulating Nucb2 has been associated with panic disorder, reported depression, depression associated with subclinical hypothyroidism, and carcinogenesis and correlated with inflammatory markers such as IL-6 and C-reactive protein as well as corticosterone." (PMID 37386441, 2023).
depression (continued). "In this study, a bacterial endotoxin (lipopolysaccharide, LPS) was administered to rats to impair their social behavior, since LPS leads to the production of inflammatory cytokines, such as IL-6, which causes neuropsychiatric disorders and depression." (PMID 36986859, 2023). "For example, increased tumor necrosis factor-α (TNF‐α) and interleukin (IL)‐1β, IL-6, and IL-17A are linked to the occurrence of anxiety and depression in coronary heart disease patients." (PMID 37878890, 2023). "Elevated IL-6 levels during childhood have been associated with increased depression in young adults." (PMID 38299049, 2023). "The polymorphic variant rs1800795 (IL6-174G/C) is associated with recent stress on current depressive symptoms and is associated with lifetime depression at a nominal significance level." (PMID 37510364, 2023). "Increased levels of IL-6 in childhood increase the risk of depression later in life, further supporting the role of inflammation in the pathogenesis and exacerbation of depression." (PMID 37069633, 2023). "The finding that increased circulating levels of IL-6 were associated with reduced depression seems counter-intuitive given multiple lines of evidence implicating IL-6 in the pathogenesis of MDD." (PMID 37085494, 2023). "In the study sample as a whole, increased IL-6 post-treatment was associated with reduced HDRS depression scores over the 6 weeks of follow-up (F(1, 102.3) = 6.74, p = 0.01)." (PMID 37085494, 2023). "Stress-induced elevation of inflammatory markers (interleukin-6 and serum intercellular adhesion molecule) has been suggested to cause sleep disturbance in depression." (PMID 36925761, 2023). "Higher levels of IL-6 has also been associated with higher concentrations of glutamate in the dorsal ACC in adolescents with depression." (PMID 37182555, 2023). "In the present study, the increased IL-6 were found to be strongly associated with stress and depression in GDM women receiving antidiabetic treatment." (PMID 37365247, 2023). "Animal studies have also shown that IL-6 trans-signaling is associated with “disease behavior” similar to depression, and inhibition of IL-6 trans-signaling alleviated pathogenic behavioral symptoms." (PMID 37828513, 2023). "A recently published first meta-analysis with a robust sample reported an adjusted association between IL-6 and future depression." (PMID 36899845, 2023). "Elevated C-reactive protein (CRP), tumor necrosis factor alpha (TNF-α), and interleukin-6 (IL-6) are the major molecular inflammatory signature associated with depression in general population." (PMID 37365247, 2023). "The increase in IL-6 in depressed patients has been already established, indicating a strong association of this pro-inflammatory marker with depression." (PMID 37754268, 2023). "Inflammation and depression are widely known to be associated, with most depressed patients exhibiting elevated inflammation markers such as cytokines (IL-1, IL-6, TNF-α) and hormones (ACTH, glucocorticoid)." (PMID 36614066, 2022). "Lymphocytes of patients with depression activate the production of IL-1b, IL-6, and TNF, and such inflammatory pathways are known to cause neuronal damage through oxidative and nitrosative stress." (PMID 35773440, 2022). "In this study, serum CRP and IL-6 were positively associated with anhedonia, whereas cortisol levels were related to both severities of depression and anhedonia in MDD." (PMID 36090246, 2022). "An association between a depression inventory test with IL-6 levels was found in depressed adolescents (18 males and 46 females, 15.6 years old)." (PMID 35736018, 2022). "Anxiety- and depression-like behavior in obese high fat diet–fed rats is associated with increases in hippocampal proinflammatory cytokine (IL-1β, IL-6, and TNF-α) levels." (PMID 35444568, 2022).
depression (continued). "Pro-inflammatory diets, such as the Western diet, can raise the levels of pro-inflammatory biomarkers (e.g., C-reactive protein (CRP), interleukin 6 (IL-6)), which can increase the risk for the development of depression." (PMID 35565951, 2022). "Children with elevated levels of IL-6 and C-reactive protein at 9 years of age are at a higher risk of depression onset by 18 years of age." (PMID 36619667, 2022). "Proinflammatory cytokines (such IL-1 and IL-6) are linked to both acute and chronic stress, and affect the severity and speed of development of depression." (PMID 36117653, 2022). "Multiple regression results show that higher IL-6 was associated with report of more somatic symptoms of depression (ß = 0.273, p = 0.002) and higher total BDI-II scores (ß = 0.221, p = 0.012)." (PMID 35651828, 2022). "We tested associations between IL-6 stress responses and a) depression symptoms and b) mental health-related quality of life (QoL) at baseline and at follow-up using linear regression analyses adjusting for age, sex, and body mass index (BMI)." (PMID 35663838, 2022). "An inflammation-dependent decline in adult neurogenesis observed in depression is mainly linked to microglia-released cytokines such as IL-1β, IL-6, TNF-α, and INF-α." (PMID 35455082, 2022). "To further explore the association of IL6 variant rs2069827 with depression and anxiety, we evaluated the main effect of this SNP in independent GWASs of these traits." (PMID 36168941, 2022). "IL-6 is a cytokine released by the immune system to help fight disease, but IL-6 also causes inflammation and has been associated with fatigue, stress, sleep, depression, pain, and mood disorders." (PMID 35624943, 2022). "LPS induces pro-inflammatory factors in the immune cells of animals, such as TNF-α, IL-1β, and interleukin-6 (IL-6), which in turn cause depression-like behaviors." (PMID 35165207, 2022). "Among the cytokines believed to be implicated in the association between stress and depression are IL-1β and IL-6, known to be potent activators of the HPA axis, which, consequently, can modulate noradrenergic and serotonergic mechanisms." (PMID 36185078, 2022). "In a similar case, relevant research suggests that the symptoms of depression are associated with interleukin-6 and D-dimer and have increased the risk of CVDs in caregivers." (PMID 35571163, 2022). "Evidence suggests a strong association between depression, anxiety, cachexia, and high levels of cytokines expression (IL-1β, IL-6, IL-10, TNF-α, INF-γ, and fractalkine [CX3X]) in cancer patients." (PMID 36067147, 2022). "We conducted a meta-analysis to explore the association between CBT and change of peripheral IL-6 levels in depressive symptoms or major depressive disorder (MDD)." (PMID 35633813, 2022). "Later studies have linked CRP and IL-6 to specific symptoms of depression and identified a potential causal link between IL-6 and depression." (PMID 35618889, 2022). "The involvement of stress-induced IL-6 increase in depression-like behaviors has been demonstrated by using IL-6 knockout mice, and a strong association between IL-6 alterations and major depressive disorder has also been shown at clinical level." (PMID 36293308, 2022). "DII has been reported to have association with numerous plasma inflammatory markers (CRP and IL6) and multiple health outcomes (stoke, depression, CVDs, metabolic risk markers, cancer and all-cause and specific-cause mortality)." (PMID 35745147, 2022). "Conclusion/relevance: This study of inflammatory biomarkers suggests the possibility of differential associations between mental health symptoms (anxiety and depression) and pro-inflammatory markers (IL-6 and IL-8)." (PMID 36158450, 2022). "The proinflammatory cytokines including IL–6, tumor necrosis factor–alpha, and IL–1, are associated with the pathophysiology of major depressive disorder in the brain." (PMID 35682430, 2022).
depression (continued). "A prior study demonstrated a substantial association between IL-6 and IL-8 and other prenatal stress, such as anxiety or depression." (PMID 36193420, 2022). "CRP and IL-6 were positively associated with anhedonia, and cortisol levels were related to both anhedonia and depression." (PMID 36090246, 2022). "Despite this potential confounding, MR studies have indicated IL-6 to be potentially causal for schizophrenia and depression." (PMID 36277463, 2022). "IL-6 levels play a crucial role in the pathogenesis of depression and have been linked to depression prognosis and treatment outcomes." (PMID 36405925, 2022). "We previously reported that FMT from Chrna7 KO mice with depression-like phenotypes caused depression-like behaviors, higher blood levels of IL-6, and downregulation of synaptic proteins in the PFC in ABX-treated mice." (PMID 35650202, 2022). "Other inflammatory markers that have been associated with clinical depression or anxiety (IL-6, TRANCE, and TWEAK) seem to be less relevant for psychological distress in adolescence." (PMID 35360574, 2022). "Blockade or deletion of D3 caused activation of those glia, with symptoms of depression and increased levels of IL-1β, IL-6, and TNF in dopaminergic neurons." (PMID 36507331, 2022). "More recently, using the MR approach Kappelmann and colleagues have reported that inflammatory markers like CRP and IL-6 are associated with specific symptoms of depression, such as suicidality." (PMID 36057695, 2022). "IL6 variants were associated with preoperative depression, somatization and with subsequent surgery." (PMID 35964023, 2022). "Cytokines, such as IL6, TNFα, and IL1β, are not only involved in the pathogenic mechanism of depression, but also of pain and fatigue." (PMID 36422176, 2022). "High serum concentrations of IL-6 and TNFα have been associated with the occurrence of depression and anxiety in patients with clinically diagnosed AD dementia." (PMID 35643540, 2022). "On the one hand, depression is associated with increased levels of inflammatory cytokines (e.g., interleukin-2 and interleukin-6), and studies have suggested that these inflammatory markers are associated with decreased BMD." (PMID 35413849, 2022). "Our study provided evidence that the capability of the antidepressant agomelatine to revert the anhedonic-like phenotype observed in the CMS model of depression is associated to the modulation of IL-6 levels and signaling." (PMID 36293308, 2022). "In contrast, another recent systematic review which included 22 studies on children and adolescents, reported both cross-sectional and prospective associations between CRP, IL-6, and clinical depression." (PMID 35360574, 2022). "IL‐6 is associated with fatigue, stress, hyperalgesia, and depression, while IL-8 mediates sympathetic hyperalgesia." (PMID 35698706, 2022). "A large-scale cohort study from the UK Biobank and Netherlands Study of Depression and Anxiety revealed an association between IL-6 and anhedonia." (PMID 36405925, 2022). "Increased TNFα and IL-6 in the cerebrospinal fluid (CSF) are also reported to be associated with the pathology of depression in systemic lupus erythematosus." (PMID 35630818, 2022). "The ‘C’ allele of rs2069835 IL6 SNP was associated with a higher risk for reoperation and also with increased level of preoperative depression and somatization." (PMID 35964023, 2022). "In depression, pro-inflammatory mediators such as IL6 have been linked to increasing the activity of the HPA axis by inducing the release of corticoliberin-releasing hormone (CRH) from the hypothalamus." (PMID 36009493, 2022). "A stable positive association between IL6 and depression was found in females, whilst in males this association was not stable." (PMID 35895279, 2022). "For example, depression and frailty were positively associated with C-reactive protein, interleukin-1, and interleukin-6." (PMID 36360934, 2022).
depression (continued). "The ‘C’ allele of IL6 SNP rs2069835 was linked to increased level of depression (mean ZDS±SD were 39.2±7.8, 42.2±9.2, and 45.3±10.1 in case of ‘T/T’, ‘T/C’ and ‘C/C’ genotypes, respectively, p=0.003 in log-additive model)." (PMID 35964023, 2022). "To this end, we generated an age-adjusted “depression-warning” level for the four main risk biomarkers identified in our statistical models (IL-6, TNF, kynurenine and QUIN)." (PMID 35078975, 2022). "Depression increased the Enterococcaceae population, NF-κB+/Iba1+ cells, expression of IL-1β and IL-6, in IBD patients, which cause more severe colitis with a disrupted intestinal barrier, and accelerated the translocation of fecal LPS into the blood." (PMID 36275694, 2022). "Fecal microbiota transplantation (FMT) from depressive patients causes depression with gut inflammation in mice through the upregulation of IL-6 and TNF-α expression." (PMID 35631220, 2022). "Increased serum concentrations of IL-6 are also observed in depression, and this finding is associated with increased severity of depressive symptoms in patients that do not respond to antidepressants." (PMID 35698706, 2022). "Over the years, the cytokine IL-6 has been linked to stress-related disorders such as depression and anxiety." (PMID 35782423, 2022). "A recent study also reported that the comethylation module in the weighted gene comethylation network analysis was associated with a history of depression and elevated IL-6 serum levels." (PMID 35628578, 2022). "Another study reported that a diagnosis of PTSD was associated with lower levels of IL-8; however, this study observed a positive association between anxiety and depression symptom severity and IL-6 levels in earthquake survivors." (PMID 36158450, 2022). "We found that depression was inversely associated with IL-6, whereas anxiety was positively associated with IL-8." (PMID 36158450, 2022). "Pro-inflammatory cytokine (IL-1β, TNF-α, IL-6) release has also been linked to depression-like behaviours and cognitive defects in mice." (PMID 34709564, 2022). "Consistently, another study in depression model mice found that rTMS reversed the down-regulation of astrocytes and inhibited high levels of IL-6, and IL-1β caused by chronic unpredictable mild stress (CUMS) in the hippocampus and prefrontal cortex." (PMID 36188478, 2022). "A cumulative meta-analysis also indicates a significant association between major depression and the level of IL-6." (PMID 35267944, 2022). "A unit increase in urinary IL-6 was associated with a decrease of 0.041 units of depression score (p = 0.013), after adjusting for demographic factors." (PMID 36299996, 2022). "The authors of the first study found that depressive disorder was associated with lower CSF levels of IL-6 and soluble-IL-6 receptor." (PMID 36172507, 2022). "For instance, serum IL-6 at age 9 years has been shown to associate with depression and PEs at age 18 years and depressive episodes, psychotic disorder and negative symptoms at age 24 years." (PMID 36277463, 2022). "This cytokine was first implicated in the etiology of sickness behavior and later linked to depressive disorder along with IL-6 and TNF." (PMID 36614020, 2022). "After the period of acute stress, the IL-6 white matter network differences were shown to be strongly associated with the interindividual variation in susceptibility to depressive disorder in healthy individuals with SLEs." (PMID 36614020, 2022). "Our analysis predicts that IL6 is a potential gene relevant to the association of bipolar disorder, depressive disorder and schizophrenia with DCM." (PMID 36385157, 2022). "Certain inflammatory markers known to be elevated in persons with depression, such as interleukin-6 (IL-6) and interleukin-10 (IL-10) have been associated with disease severity and mortality in patients infected with SARS-CoV-2." (PMID 34066585, 2021).